IL4 (interleukin 4)
Description:
Cytokine secreted primarily by mast cells, T-cells, eosinophils, and basophils that plays a role in regulating antibody production, hematopoiesis and inflammation, and the development of effector T-cell responses. Induces the expression of class II MHC molecules on resting B-cells. Enhances both secretion and cell surface expression of IgE and IgG1. Also regulates the expression of the low affinity Fc receptor for IgE (CD23) on both lymphocytes and monocytes. Positively regulates IL31RA expression in macrophages. Stimulates autophagy in dendritic cells by interfering with mTORC1 signaling and through the induction of RUFY4. In addition, plays a critical role in higher functions of the normal brain, such as memory and learning (By similarity). Upon binding to IL4, IL4R receptor dimerizes either with the common IL2R gamma chain/IL2RG to produce the type 1 signaling complex, located mainly on hematopoietic cells, or with the IL13RA1 to produce the type 2 complex, which is also expressed on nonhematopoietic cells. Engagement of both types of receptors initiates JAK3 and to a lower extend JAK1 phosphorylation leading to activation of the signal transducer and activator of transcription 6/STAT6.
Synonyms: IL-4; BSF-1; BSF1; BCGF1; BCGF-1; MGC79402
Tractability: Antibody: a drug acting on it is in phase 2 or 3 trials; its Gene Ontology location is reachable by antibodies, with high confidence; UniProt places it where antibodies can reach, with medium confidence; UniProt predicts a signal peptide or a membrane-spanning region.
Target class: Secreted protein
Safety:
Unwanted effects reported when the protein is acted on. In parentheses: how it was acted on, where the effect was seen, and who reports it.
aspirin-induced decline in forced expiratory volume in 1 s (FEV1) (source: ClinPGx)
Gene: Protein-coding gene on chromosome 5 (132,673,986 to 132,682,678, forward strand). Ensembl gene ENSG00000113520.
Subcellular location: Secreted
Pathways (Reactome):
Developmental Biology: Differentiation of naive CD4+ T cells to T helper 1 cells (Th1 cells); Differentiation of naive CD4+ T cells to T helper 2 cells (Th2 cells)
Immune System: Interleukin-18 signaling; Interleukin-4 and Interleukin-13 signaling
Gene Ontology:
Molecular function: cytokine activity; protein binding; growth factor activity; interleukin-4 receptor binding; cytokine receptor binding
Biological process: cell surface receptor signaling pathway via JAK-STAT; dendritic cell differentiation; interleukin-4-mediated signaling pathway; macrophage activation; myeloid dendritic cell differentiation; negative regulation of cellular response to transforming growth factor beta stimulus; negative regulation of complement-dependent cytotoxicity; negative regulation of DNA-templated transcription; negative regulation of endothelial cell apoptotic process; negative regulation of epithelial cell migration; negative regulation of inflammatory response; negative regulation of transcription by RNA polymerase II; positive regulation of cell migration; positive regulation of cell population proliferation; positive regulation of DNA-templated transcription; positive regulation of interleukin-10 production; positive regulation of interleukin-13 production; positive regulation of T cell differentiation; positive regulation of T-helper 2 cell cytokine production; positive regulation of transcription by RNA polymerase II; T cell activation; B cell differentiation; cholesterol metabolic process; immune response; negative regulation of apoptotic process; and 23 more
Cellular component: extracellular region; interleukin-4 receptor complex
Genetic constraint (gnomAD): Loss-of-function variants: 6 observed, 14.86 expected, observed/expected ratio (o/e) 0.4, 90% interval 0.22 to 0.8. The upper end of that interval is the gene's LOEUF score, 0.8, which puts it in group 3 of 6, group 1 being the genes least tolerant of losing a copy. Missense variants: 143 observed, 156.24 expected, observed/expected ratio (o/e) 0.92, 90% interval 0.8 to 1.05. Synonymous variants: 68 observed, 66.46 expected, observed/expected ratio (o/e) 1.02, 90% interval 0.84 to 1.25.
Homologues: Orthologues: chimpanzee IL4 (99% identical), macaque IL4 (92% identical), pig IL4 (61% identical), rabbit IL4 (52% identical), dog IL4 (49% identical), rat Il4 (42% identical), guinea pig Il4 (41% identical), mouse Il4 (39% identical).
Diseases named in the same sentence as IL4 in open-access papers:
IL4 is named in the same sentence as 1,075 diseases in open-access papers, as found by Europe PMC text mining. Sharing a sentence is not in itself a finding about the gene and the disease. The quoted sentences say what the papers report.
asthma (1,707 papers, 2003 to 2026). "IL-4 and IL-5 are largely produced by activated Th2 cells, contributing to humoral immunity and often linked to allergies and asthma." (PMID 41313182, 2026). "Recent studies have shown that the control of IgE class switching in asthma is closely associated with TFH cells producing IL‐4 and IL‐13." (PMID 41568067, 2026). "WGCNA revealed a total IgE-associated gene module, suggesting downregulated IgE and IL-4 mRNA in non-T2 asthma." (PMID 41601686, 2026). "The Th2 inflammatory pathway is frequently upregulated during these infections, associated with increased production of cytokines such as IL-4, IL-5, and IL-13, which aggravate asthma symptoms." (PMID 41738365, 2026). "T helper cell 2, i.e., Type 2 (T2) high asthma and CRSwNP are linked to eosinophils and cytokines, interleukin (IL)-4, IL-5, IL-13, while Type 2 low endotype involves Th17 pathways and neutrophilic inflammation." (PMID 41213931, 2025). "IL-4 and IL-13 are key asthma pathogenetic cytokines and are both implicated directly in bronchial inflammation and airway remodeling." (PMID 40283665, 2025). "In the pathophysiological association between obesity and asthma, adipose tissue eosinophils, IL-4, and leptin form a key regulatory network via the immune-metabolic axis." (PMID 41244254, 2025). "In contrast, exposure to Th2-associated cytokines (e.g., IL4 or IL13) drove eosinophils polarization toward type 2 eosinophils, resulting in an increase in IL4/13 signaling and genes associated with asthma." (PMID 40025520, 2025). "In a Tunisian population, the rs713599 A allele was associated with protection against asthma, a condition influenced by IL-4 expression." (PMID 40658679, 2025). "Estrogenic EDCs like BPA and phthalates skew the immune balance toward Th2 polarization by increasing IL-4, IL-5, and IL-13 production, thereby heightening the risk of allergic diseases, including asthma and atopic dermatitis." (PMID 41020825, 2025). "The underlying pathology in most asthma cases involves type 2 inflammation, predominantly orchestrated by T helper type 2 (Th2) cells secreting interleukins (IL‐4, IL‐5, and IL‐13), eosinophils, and mast cells, among other factors." (PMID 41200848, 2025). "The hallmark of the Th2-high asthma was IL4, IL5, and IL13, and the mouse Elisa kit was used to screen the Th2 cytokines in BALF and serum of different stages mouse models first (data not shown)." (PMID 40503233, 2025). "By targeting immunoglobulin E (IgE), thymic stromal lymphopoietin (TSLP), and specific cytokines such as IL-5, IL-4, and IL-13, biologics offer more precise and personalized treatment in patients with severe asthma and associated comorbidities." (PMID 41156259, 2025). "Polymorphisms in genes for alarmins (TSLP and IL‐33) and type 2 cytokines (IL‐4 and IL‐13) influence asthma risk and severity, although many genetic contributors remain unidentified." (PMID 40679787, 2025). "The inflammation in bronchial tubules of lungs worsens the asthma which is also associated with Th2 cytokines release such as IL‐4 and IL‐13, that resultantly involve in remodeling of markers related to M2 macrophages." (PMID 39830909, 2025). "For example, gene variations associated with the IL-4/IL-13 pathway are linked to asthma susceptibility." (PMID 40313547, 2025). "Asthma is a persistent inflammatory condition of the airways linked to type 2 cytokines, such as IL-4, IL-5, and IL-13." (PMID 40558541, 2025). "Microbiome analysis revealed an increased abundance of Leptotrichia and Parasutterella in asthma patients, both positively associated with IL-4." (PMID 40871265, 2025). "Imbalances in IL-4 and IL-13 are implicated in the development of inflammatory diseases like UC and asthma." (PMID 40333150, 2025). "For instance, Th2-driven asthma, which is characterized by elevated levels of IL-4 and IL-13, is associated with histone hyperacetylation at H3K9 and trimethylation at H3K4." (PMID 40806756, 2025).
asthma (continued). "Th2 cells are pathogenic in asthma because they produce high amounts of the prototypical type 2 cytokines IL-4, IL-5, IL-9, and IL-13." (PMID 41145900, 2025). "IL-4 activated B cells can switch to IgE, causing mast-cell and basophil-mediated bronchial hyperreactivity." (PMID 41550933, 2025). "Cytokine activity is closely associated with asthma, as cytokines like IL-4, IL-5, and IL-13 can promote mucus overproduction and bronchial hyperresponsiveness, which are symptoms of asthma." (PMID 40266878, 2025). "Children who have suffered from RSV bronchiolitis have been found to have a significantly higher frequency of IL-4 - producing T cells in response to cat allergens(Feld), which is closely associated with an increased risk of asthma and wheezing." (PMID 40636260, 2025). "By inhibiting IL-4 and IL-13 signaling pathways, dupilumab addresses key mechanisms underlying asthma pathophysiology." (PMID 40564060, 2025). "Recent data indicate that the asthma-associated cytokines IL-4 and IL-13 can reprogram lung-innervating nociceptor neurons to adopt a pro-allergic phenotype 24." (PMID 39229121, 2025). "Th2 immune responses are characterized by the increased production of IL-4, IL-5, and IL-13, and have been associated with RV infection in asthma." (PMID 39941446, 2025). "Asthma pathology is heterogeneous; a major subtype is type 2 (T2) high asthma, which is driven by T helper 2 (Th2) lymphocytes and T2 cytokines (IL-4 and IL-13), and is often associated with eosinophilia and elevated immunoglobulin E (IgE)." (PMID 40843371, 2025). "Another possibility is the use of dupilumab (IL-4/IL-13 receptor blocker), which has shown promising results in the treatment of various eosinophil-associated diseases including atopic dermatitis, asthma, nasal polyps, and eosinophilic esophagitis." (PMID 40860650, 2025). "The most common asthma variant in children, T2-high asthma, is characterized by atopy, eosinophilic inflammation, elevated Th2 cytokines (IL-4, IL-5, and IL-13), and leukocyte recruitment driven by CD4 + T-cells, mast cells, and eosinophils." (PMID 40806181, 2025). "For instance, eosinophilic airway inflammation associated with TH2 cytokines (IL-4, IL-5, and IL-13) and/or Ig E is an underlying pathological mechanism in both chronic rhinosinusitis with nasal polyps and asthma." (PMID 38919942, 2024). "For example, Interleukin-4 (IL4), a CK critical to developing T-cell-mediated humoral immune responses associated with allergy and asthma, can exert its actions through different receptors." (PMID 38789577, 2024). "There are abundant evidences that asthma is linked to Th2-type inflammatory responses induced by allergic stimuli, and the expression of interleukin (IL)-4 is crucial for the development of Th2 immune responses." (PMID 38594768, 2024). "The pathogenesis of asthma has been linked to an imbalance between Th2 and Th1 cells, resulting in increased levels of interleukin (IL)-4, IL-5, and IL-13 and decreased levels of interferon (IFN)-γ." (PMID 39539452, 2024). "Th2 cells are best known for producing IL-4, IL-5, and IL-13 and are associated with host defenses against parasites and involvement in allergies and atopic diseases such as asthma." (PMID 39481080, 2024). "Elevated levels of IL-13, IL-4, and IL-5 are particularly associated with asthma, contributing to airway hyperresponsiveness, eosinophil recruitment, and mucus production." (PMID 39902079, 2024). "In type 2-high asthma, type 2 inflammation is present with its associated cytokines IL-4, IL-5, and IL-13, high levels of blood and/or sputum eosinophils, and elevated FeNO." (PMID 39765793, 2024). "Additional asthma therapies, also approved for children, use biologicals such as Omalizumab or Dupilumab which target IgE or asthma-associated cytokines such as IL-4 and IL-13, respectively." (PMID 38172451, 2024).
asthma (continued). "There is increasing evidence that asthma is associated with persistent low-grade inflammation, indicated by higher levels of inflammatory markers such as IL-4, IL-5, and IL-13." (PMID 39372270, 2024). "Studies have revealed that estrogen can enhance the production of type 2 cytokines, such as interleukin-4 (IL-4) and interleukin-5 (IL-5), which play critical roles in promoting airway inflammation and allergic responses associated with asthma." (PMID 39026347, 2024). "Th2-driven (IL-4/IL-13) airway diseases, such as asthma, cause goblet cell metaplasia, accompanied by increased mucus production and airway secretions." (PMID 39255033, 2024). "Th2 cells promote airway inflammation by production of a range of cytokines including IL-4, IL-5, IL-9, IL-13 and IL-25, which together are responsible for the development of hallmark features of asthma." (PMID 39598682, 2024). "To determine the mechanisms underlying these differences, we treated HASM cells with asthma-related cytokines, several of which [IL-4/13 and transforming growth factor–β (TGFβ)] are known to directly increase ASM contractility." (PMID 39612338, 2024). "Increased IL-4 and IL-13 levels over healthy controls are a hallmark of T2-high asthma and are important in eCOPD as well." (PMID 39766355, 2024). "Asthma is generally a moderate disease characterized by eosinophilia and dominance of T helper 2 (Th2) cells and their hallmark cytokines IL-4, IL-5, and IL-13." (PMID 38177117, 2024). "Briefly, as the induction of asthma is a complex topic, Th2-high asthma represents the mechanism of IL-4, IL-5, and IL-13 associated asthma, which induces roughly 50% of mild-to-moderate asthma and the majority of severe asthma inflammation." (PMID 39239645, 2024). "Type 2 cytokines (e.g., IL-13, IL-5, and IL-4) facilitate asthma’s hallmark characteristics (e.g., susceptibility to exacerbations, IgE production, AHR, IgE production, mucus hypersecretion, and eosinophilia)." (PMID 38245791, 2024). "The sensitised mice exhibited an increased expression of the Th2-like and asthma-associated cytokines, IL-4, IL-5, and IL-13, as well as mRNA encoding for pro-inflammatory TNF-α and the Th1 cytokine IFN-γ." (PMID 38765484, 2024). "In asthma, increased mitochondrial dysfunction has been observed, and asthma specific cytokines (IL-4) are associated with increased mitochondrial damage." (PMID 39595165, 2024). "The equilibrium between mucin secretion and its removal is delicate; disturbances in this balance, often caused by cytokines like IL-4 and IL-13, are associated with diseases such as asthma, AR, and CRS." (PMID 38680486, 2024). "Specifically, GSEA analysis revealed GdT17 cells in asthma model were associated with various signaling pathways, including IL4/IL13 signaling, IFN-γ response and inflammatory response." (PMID 38317239, 2024). "In asthma model mice, deficiency of both IL-4 and IL-13 markedly reduced the number of eosinophils in airway, and induced blood eosinophilia." (PMID 38745653, 2024). "This disease has mainly been associated with Th2 cell cytokines, i.e., IL-4, IL-5, and IL-13, however recent developments have led to a terminology of Th2-high and Th2-low asthma." (PMID 39239645, 2024). "A combined effect on the risk of developing asthma was observed with the presence of polymorphisms in the interleukin 4, β2-adrenergic receptor, and ADAM33 genes." (PMID 38396994, 2024). "Comparative analysis of allele and genotype frequenciesbetween the cohort of asthma patients and controls revealedstatistically significant differences in the SNPs distribution inthe promoter regions of IL4 rs2243250 and IL13 rs1800925." (PMID 37465198, 2023). "The development of asthma is linked to an excess production of Th2 cytokines, specifically IL-4 and IL-5." (PMID 37760982, 2023).